NLRP3 (NLR family pyrin domain containing 3)
Diseases named in the same sentence as NLRP3 in open-access papers (continued):
Sharing a sentence is not in itself a finding about the gene and the disease.
colitis (continued). "TiO2 has been shown to exacerbate experimental colitis via NLRP3 pathways, and multiple studies report NP-associated dysbiosis and immune perturbation." (PMID 41155883, 2025). "The natural derivative Palmatine ameliorated DSS-induced colitis by promoting mitochondrial autophagy-mediated NLRP3 inflammasome inhibition." (PMID 40842999, 2025). "Gene interference investigated NLR family pyrin domain containing 3 (NLRP3) involvement in UAF1-induced colitis inflammation." (PMID 39966502, 2025). "In vivo studies in mice with colitis demonstrated that after NLRP3 stimulation, hMSCs exhibit enhanced protective effects." (PMID 40433382, 2025). "Rev‐erb modulates the production of pro‐inflammatory cytokines including IL‐6 and regulates colitis via NF‐κB/Nlrp3 axis." (PMID 40911428, 2025). "This compound alleviates colitis by inhibiting the activation of the NLRP3 inflammasome, as well as mitigating pyroptosis and apoptosis." (PMID 40271055, 2025). "We further found that in A. shahii As360-treated colitis mice, the expression of mtor and Nlrp3 genes was reduced while the expression of mTOR inhibitor gene Ddit4 was increased." (PMID 39936902, 2025). "Exogenous agents like a butyrate-melatonin complex can halt colitis progression by dual modulation of the microbiome and the NLRP3/caspase-1 pathway, effectively re-educating macrophages towards an anti-inflammatory phenotype." (PMID 41150761, 2025). "Taken together, these data suggest that VANGL2 alleviates the progression of DSS-induced colitis in mice by blocking the NLRP3 inflammasome activation." (PMID 39899477, 2025). "In LPS-induced septic shock and dextran sodium sulfate (DSS)-induced colitis, S-nitrosoglutathione reductase regulates NLRP3 transcription through S-nitrosylation and the modulation of mitogen-activated protein kinase 14 activity." (PMID 40307577, 2025). "Atranorin administration protected against NLRP3 inflammasome-driven diseases and ameliorated colitis in vivo by improving epithelial barrier function and reducing IL-1β and IL-18 production." (PMID 40869366, 2025). "Collectively, these findings indicate that NDGA ameliorates colitis development by inhibiting GSDMD/NR4A1/NLRP3-dependent inflammatory macrophage activation." (PMID 40596758, 2025). "Subsequently, isobutyric acid was found to suppress NLRP3 inflammasome overactivation and ameliorate colitis in vivo while also attenuating inflammatory injury in vitro." (PMID 41171006, 2025). "This aligns with reports of GPR30-mediated NLRP3 inflammasome suppression in cerebral ischemia and colitis models, though our study uniquely implicates IFI16/NLRC4 as key effectors in SAH." (PMID 40726812, 2025). "For the first time that spexin ameluates acetic acid-induced colitis in rats by modulating the NF-κB/NLRP3 signaling pathway, reducing oxidative damage, enhancing antioxidant capacity, and suppressing inflammation." (PMID 40320895, 2025). "Another study also found that Galectin-3 expression contributes to acute DSS-induced colitis by activating the NLRP3 inflammasome and producing IL-1β in macrophages." (PMID 40534879, 2025). "Regarding IL-18, sanguinarine relives colitis by inactivating NLRP3-Caspase1/IL-1β pathway, which in turn upregulates IL-18 to exert proinflammatory effects." (PMID 40092732, 2025). "The pretreatment with A. muciniphila alleviated the phenotype of DSS-induced colitis mice through activating NLRP3 and decreasing the expression of pro-inflammatory cytokines (IL1β, IL-6) and chemokines MCP-1." (PMID 41488633, 2025). "Research indicates that JMJD3 targets Nrf2 to modulate NLRP3 inflammasome activation, exacerbating colitis progression in mice treated with dextran sodium sulfate." (PMID 40801194, 2025). "ER stress–induced exosomes derived from IECs, or macrophages have been shown to activate NF-κB and the NLRP3 inflammasome in murine models of colitis, supporting their role in amplifying mucosal inflammation." (PMID 41383462, 2025).
colitis (continued). "Treatment with mesalamine significantly reduced mTOR levels by 49.75% (F = 528.4, p = 0.004) and downregulated NLRP3 expression by 40.32% (F = 66.14, p = 0.008) compared to the colitis group." (PMID 40387460, 2025). "In a mouse model of dextran sulfate sodium (DSS)-induced colitis, genistein significantly suppressed NLRP3 inflammasome activation via the TGR5–cAMP signaling axis, leading to reduced IL-1β secretion and improved clinical outcomes." (PMID 41433336, 2025). "The compound demonstrated significant efficacy in endotoxemia and colitis models, supporting its therapeutic potential for NLRP3‐mediated disorders." (PMID 40948397, 2025). "Lac16 administration significantly ameliorated colitis symptoms while restoring intestinal barrier integrity, promoting anti-inflammatory macrophage polarization, and suppressing NLRP3 inflammasome overactivation." (PMID 41171006, 2025). "The absence of NLRP3 or the inhibition of IL-1 eliminates the colitogenic effect of Klebsiella aerogenes in mice, highlighting the crucial role of the NLRP3–IL-1β axis in the development of oral commensal pathobiont-driven colitis." (PMID 41149694, 2025). "In the present study, the PTX group exhibited a significant increase in colonic AMPK expression and a significant decrease in colonic expression of NLRP3 and mTOR when compared to the colitis group." (PMID 40387460, 2025). "When treated with dextran sulfate sodium (DSS), mice with knockout of caspase-1 and NLRP3 showed considerable improvement in colitis." (PMID 40041420, 2025). "Together, this study described that A. muciniphila plays a protective role in colitis through activating the NLRP3 inflammasome for inducing protective immunity." (PMID 41488633, 2025). "Beyond the direct effects of the NLRP3‐GSDMD axis on NETosis modulated by LCA, NLRP3 signaling also contributes to O. splanchnicus‐induced inhibition of inflammation and barrier repair in colitis." (PMID 40990446, 2025). "As anticipated, MCC950 decreased NLRP3 expression in colon tissues of mice with acute colitis and notably suppressed the upregulation induced by rPrdx1." (PMID 40715057, 2025). "Recent studies have shown that NLRP3 knockout has a protective effect on dextran sulfate sodium (DSS)-induced colitis mice, and NLRP3 inhibitors can effectively improve the occurrence of colitis." (PMID 39334766, 2024). "Naringin and Procyanidin, two powerful antioxidation flavonoids, alleviated disease activity in DSS-induced colitis models, suppressing the activation of NF-κB signaling and NLRP3 inflammasome activation." (PMID 39684769, 2024). "Sacral nerve stimulation has been shown to improve DSS-induced colitis by increasing macrophage autophagy and suppressing the activation of NLRP3 inflammatory bodies." (PMID 38892354, 2024). "In turn, the overactivation of NLRP3 induces colitis through the upregulation of pro-inflammatory cytokines within intestinal epithelial cells, sustained macrophage activity, and recruitment of effector T cells." (PMID 39201713, 2024). "Summary, CQ exerts an excellent ameliorating effect on the DSS-induced NLRP3 inflammasome-related colitis." (PMID 39701924, 2024). "TXYF regulated macrophage polarization to ameliorate DSS-induced colitis via NF-κB/NLRP3 signaling pathway." (PMID 38271090, 2024). "In the intestinal epithelium of the dextran sodium sulfate (DSS)-induced colitis mice, inhibition of IP activity significantly ameliorated disruptive symptoms by downregulating protein levels of NLRP3 and secretion of inflammatory cytokines." (PMID 38667290, 2024). "Suppression of CD82 decreased the pathogenesis of colitis by increasing NLRP3 inflammasome activation via BRCC3-dependent K63 deubiquitination." (PMID 38892354, 2024). "Increasing evidence have supported the abnormal activation of the NLRP3 inflammasome in dextran sulfate sodium (DSS)‐colitis and TNBS‐colitis." (PMID 39119947, 2024).
colitis (continued). "Induced NLRP3 expression combined with increased IL-1β levels were found as the predominant features for the initiation of colitis in miR-223 KO mice." (PMID 38323035, 2024). "Our results revealed that DCA significantly reduced the level of NFATC1 by 50% and NLRP3 by 40% in oxazolone-induced colitis." (PMID 37902927, 2024). "Observations show that CD82 inhibits NLRP3 inflammasome activation both in vitro and in vivo, and in rodents, CD82 deficiency reduces the severity of colitis." (PMID 38892354, 2024). "DCA significantly reduced the level of cleaved caspase-1 by 50% in oxazolone-induced colitis, indicating effective reversal of caspase-1 activation in colitis through reducing NLRP3 protein level." (PMID 37902927, 2024). "STAT1 in macrophages exacerbated inflammatory progression by upregulating NLRP3 expression in a mouse model of colitis." (PMID 38315275, 2024). "In this study, inflammasome-associated factors, including p-STAT3, NLRP3, IL-1β, and caspase-1, were significantly enhanced in a DSS-induced mouse colitis model." (PMID 39329121, 2024). "In mouse models of colon cancer induced by azoxymethane (AOM) and dextran sulfate sodium (DSS), NLRP3-knockout mice exhibited a higher likelihood of developing colon polyps and were more susceptible to AOM-DSS-induced colitis-associated colon cancer." (PMID 39456655, 2024). "In mice with DSS-induced colitis, VI-16 intervened by inhibiting NLRP3 inflammasome-related IL-1β release and reducing oxidative stress." (PMID 39684769, 2024). "It activates the NLRP3 inflammasome by reducing the enrichment of H3K27me3 in the Nrf2's promoter, resulting in elevating Nrf2 levels and subsequent promotion of NLRP3 inflammasome assembly, ultimately contributing to colitis progression." (PMID 39315124, 2024). "E. cava extract was previously shown to reduce the effect of NLRP3/NF-κB pathway activation and inflammation in colitis." (PMID 38671856, 2024). "C646 is an inhibitor of histone acetyltransferase p300, which ameliorates inflammation in a DSS-induced colitis model by affecting NLRP3 inflammasome assembly and activation." (PMID 39684769, 2024). "Another study has shown that Gal-3 inhibitor DAVANAT® reduces cholangitis induced by Novosphingobium aromaticivorans and DSS-induced colitis by reducing the activation of NLRP3 inflammasome and expression of IL-1β in macrophages." (PMID 39125698, 2024). "Xu and co-workers reported that C646 impaired NLRP3 inflammasome activation through the suppression of ASC oligomerization, inhibiting interactions with NLRP3 and ameliorating experimental colitis." (PMID 39684769, 2024). "Protein mediators involved in the multiple inflammasome pathways that activate GSDMD, including NLRP1, NLRP3, and AIM2, have been shown to attenuate the development of colitis-associated colorectal cancer (CAC) in mice." (PMID 38898209, 2024). "Further, IL-1β- and NLRP3-null mice have shown significantly reduced inflammatory response and colitis development." (PMID 39769450, 2024). "Based on these findings, it seems that probiotic-based treatment for colitis benefits from NLRP3’s protective properties." (PMID 39323474, 2024). "For example, prophylactic treatment with an S100A9 inhibitor has been shown to reduce colitis-induced neuroinflammation and NLRP3−/− mice showed attenuated neuroinflammation and neurological dysfunction following DSS." (PMID 39021817, 2024). "It has been demonstrated that treatment with MCC950 improved colitis in mice with an IRGM deficiency, blocking NLRP3 inflammasome activation." (PMID 39684769, 2024). "It was proven that the Cinnamaldehyde (CA) ameliorated DSS-induced colitis by reducing the expression levels of miR-21 and miR-155 in the colon, and, as a consequence, blocked the activation of the NLRP3 inflammasome." (PMID 39684769, 2024).
colitis (continued). "Salidroside (Sal), Palmatin, and Cinnamaldehyde (CA) act to alleviate the disease activity index (DAI) in DSS-induced colitis mouse models by downregulating NLRP3 inflammasome activation and restoring the expression levels of pro-inflammatory mediators." (PMID 39684769, 2024). "It has been reported that GDF11 can ameliorate experimental colitis by inhibiting NLRP3 inflammasome activation." (PMID 38715043, 2024). "Taken together, the upregulation of eNAMPT and NOX2 subunits led to NLRP3 inflammasome activation in colitis macrophages, which contributes to severe colitis." (PMID 38879692, 2024). "In this study, we examined the effects of NLRP3 deficiency or pharmacological inhibition using the reported inhibitor, GLB, in models of DSS-induced colitis and AOM/DSS-induced colon tumorigenesis." (PMID 39519191, 2024). "Gal-3 is known to play a pivotal pro-inflammatory role during the induction phase of acute colitis, facilitating NLRP3 inflammasome activation and subsequent IL-1β production." (PMID 38172822, 2024). "Studies on experimental models of colitis report contradictory results regarding the role of NLRP3 in IBD pathogenesis." (PMID 39684769, 2024). "It has been shown that activation of inflammasome and IL-18 signaling pathway has a strong protective effect in colitis-associated colorectal cancer, among which NOD-like receptor protein 3 (NLRP3) is one of the most studied inflammasome." (PMID 39325798, 2024). "Schisandrin B can not only relieve intestinal inflammation, but also suppress the leucine-rich repeat, pyrin domain-containing 3 (NLRP3) inflammasome, and nucleotide-binding oligomerization domain in vivo and vitro model of colitis." (PMID 39086391, 2024). "In IBD, miR-223 inhibited NLRP3 expression and reduced IL-1β production, ameliorating colitis in a mouse model." (PMID 39684769, 2024). "The possibility that the NLRP3 inflammasome signaling pathway plays a key role in ST36's remission of acute colitis was again validated." (PMID 39119947, 2024). "WT161, a specific inhibitor for HDAC6, alleviated colonic inflammation and intestinal injury in DSS-induced colitis mice via NLRP3 inflammasome suppression." (PMID 39684769, 2024). "In the current experiment, this colitis model was used to verify the inhibitory effect of CQ on NLRP3 inflammasome activation in vivo." (PMID 39701924, 2024). "Studies indicate that Gal-3 induces NLRP3 (NLR family pyrin domain-containing 3) inflammasome activation in macrophages in a model of dextran sulfate sodium (DSS)-induced colitis, while macrophages of Gal-3 knock-out mice produce less TNF-α and IL-1β." (PMID 39125698, 2024). "Numerous studies have found that NLRP3 inflammasome is a vital component of intestinal inflammation in a DSS colitis model." (PMID 38667290, 2024). "Dihydroartemisinin (DHA) is another compound, derivative of artemisinin, which protects against acute colitis via suppressing NLRP3 inflammasome activation and NF-κB and p38 MAPK signaling." (PMID 39684769, 2024). "Administration of nanoparticle with overexpressed miR-223 showed amelioration of experimental colitis, and decrease of NLRP3 levels and IL-1β secretion." (PMID 38323035, 2024). "Despite numerous studies investigating the impact of the NLRP3 inflammasome on colonic inflammation, its role in colitis remains contentious." (PMID 39519191, 2024). "For instance, walnut oil has been shown to alleviate DSS-induced colitis in mice by inhibiting NLRP3 inflammasome activation and regulating gut microbiota." (PMID 39203780, 2024). "Based on that, we measured if DCA-induced reduction in the expression level of NLRP3 would reduce the level of cleaved caspase-1 and hence IL-1β level in oxazolone-induced colitis as measured by Western Blot." (PMID 37902927, 2024).
colitis (continued). "Generally, findings of the current study aligns very well with previous researches stating the mitigation of experimental colitis and suppression of mucosal inflammation through inhibition of NLRP3 inflammasome activation." (PMID 37841914, 2023). "A variety of active components of traditional Chinese medicine, including flavonoids, polysaccharides, polyphenols, terpenoids, and saponins, can protect against UC-related colitis symptoms by regulating NLRP3-related pathways." (PMID 37849728, 2023). "Overexpression of the NLRP3 inflammasome exacerbates colitis and plays a pivotal role in intestinal inflammation in DSS-induced colitis." (PMID 38138587, 2023). "Another inhibitor of HDAC6 also exhibited protective effects on colitis in mice by preventing NLRP3 inflammasome activation." (PMID 38155235, 2023). "Inhibition of NLRP3 or Caspase-8 activity ameliorated colitis, with reduction in NLRP3 inflammasome activation, cell death markers, activated T-cells and macrophages, improved histology, and increased abundance of Clostridium cluster XIVa species." (PMID 36656595, 2023). "We show that AIEC and NSAIDs combine to induce/exacerbate colitis and cell death via the NLRP3 inflammasome and Caspase-8 with evidence of NLRP3-Caspase-8 cross-talk contributing to this overall phenotype." (PMID 36656595, 2023). "In fact, an anti-inflammatory effect on DSS-induced colitis in mice has been reported by inhibiting the NLRP3 inflammasome." (PMID 37298868, 2023). "Following these findings, nanoparticle-mediated overexpression of miR-223 has been developed to attenuate experimental colitis, NLRP3 activation, and IL-1β release." (PMID 37891577, 2023). "Lastly, RRx-001, a novel dinitroazetidine small molecule, has display therapeutic function for NLRP3-driven colitis by covalent binding to Cys 409 of NLRP3 via its bromoacetyl group." (PMID 37891577, 2023). "In DSS mice, the degree of colitis in NLRP3 knockout mice is milder than that in wild mice, partly due to the reduced levels of proinflammatory cytokines." (PMID 37370025, 2023). "In a mouse model of colitis induced by dextran sodium sulfate, the NLRP3 inflammasome was activated and shown to be required for production of IL-1β and IL-18, and for dextran sodium sulfate-induced colitis." (PMID 36669831, 2023). "Analogously, LGG-derived extracellular vesicles attenuated inflammation through inhibition of TLRs/NF-κB/NLRP3 pathway in a murine colitis model." (PMID 36918929, 2023). "To further confirm the dependence of chlorogenic acid’s alleviation of DSS-induced colitis on the intervention of the Nlrp3 inflammasome, we verified in CY-09-, an inhibitor of Nlrp3, treated mice." (PMID 37813835, 2023). "Sinapic acid also reduced the signs of DSS-induced colitis in mice by controlling NLRP3 inflammasome." (PMID 37849728, 2023). "A protective effect of ginsenoside Rk3 on DSS-induced colitis is achieved by inhibiting NLRP3 inflammasome expression and protecting intestinal barrier function." (PMID 37849728, 2023). "It was reported that Akk activated NLRP3, upregulated RORγt+ Treg cells, and improved the microbial community to alleviate colitis." (PMID 38004116, 2023). "In a mouse model of azoxymethane (AOM)-dextran sulfate sodium (DSS)-induced colon cancer, NLRP3 knockout mice were more likely to develop colon polyps and were highly sensitive to AOM-DSS-induced colitis-associated colon cancer." (PMID 37497237, 2023). "The mechanism is that G-Rd inhibits DSS-induced experimental colitis in mice by promoting the AMPK-ULK1-p62 axis-driven mitochondrial autophagy-mediated NLRP3 inflammasome inactivation and reducing macrophage IL-1β secretion." (PMID 37849728, 2023). "DP inhibited the activation of the NF‐κB/NLRP3 pathway and upregulated the Nrf2/HO‐1 pathway to protect against colitis." (PMID 37970386, 2023). "Oridonin, a bioactive diterpenoid, is another covalent inhibitor of NLRP3 that was shown to suppress experimental colitis in mice." (PMID 37681916, 2023).